THSD7A (thrombospondin type 1 domain containing 7A)
Diseases named in the same sentence as THSD7A in open-access papers (continued):
Sharing a sentence is not in itself a finding about the gene and the disease.
leukemia (1 paper, 2023). A malignant (clonal) hematologic disorder, involving hematopoietic stem cells and characterized by the presence of primitive or atypical myeloid or lymphoid cells in the bone marrow and the blood. "In our series, the clinicopathological features of T-ALL and concurrent MN negative for THSD7A and NELL1, and segmentally and mildly positive for PLA2R indicated true paraneoplastic MN, although the exact pathogenetic link between the leukemia and MN remained unexplored." (PMID 37550626, 2023).
melanoma (1 paper, 2026). A malignant, usually aggressive tumor composed of atypical, neoplastic melanocytes. "A quantitative proteomic comparison of exosomes purified from control and endoglin-KD melanoma cells revealed that the filopodia regulatory transmembrane molecule thrombospondin type 1 domain containing 7A (THSD7A) is reduced in endoglin-KD exosomes." (PMID 41532547, 2026). "Indeed, recombinant human THSD7A fully rescued the filopodia defects of endoglin-KD for both HT1080 and B16F1 melanoma cells." (PMID 41532547, 2026).
metastatic carcinoma (1 paper, 2019). A carcinoma which has spread from the original site of growth to another anatomic site. "Moreover, a patient with THSD7A positive MN was diagnosed with mixed adenoneuroendocrine carcinoma of the gallbladder, the positive expression of THSD7A was detected in the tumor tissues as well as the lymph nodes with the metastatic carcinoma." (PMID 31443644, 2019).
renal neoplasia (1 paper, 2025). "The two cases of THSD7A-associated MN showed, in fact, a strong correlation with neoplastic pathology: one case of adenocarcinoma and one case of renal neoplasia." (PMID 40612566, 2025).
Squamous Cell Carcinoma of the (1 paper, 2023). "For that reason, we examined the role of THSD7A as a potential biomarker in squamous cell carcinomas of the lung and the association between THSD7A and FAK in this tumor entity." (PMID 37445817, 2023).
syphilis (1 paper, 2024). A contagious bacterial infection caused by the spirochete Treponema pallidum. "Anti-PLA2R and anti-THSD7A autoantibodies were both negative, and no secondary cause was identified, i.e., normal PET-CT, negative HBV, HCV, syphilis, and HIV serologies, normal serum complement levels, and no detectable autoantibodies." (PMID 38540991, 2024).
thyroid tumor (1 paper, 2016). A benign or malignant neoplasm affecting the thyroid gland. "40% of THSD7A-related MN was secondary to thyroid tumor or HBV infection." (PMID 27634909, 2016).
cancer (42 papers, 2013 to 2026). A tumor composed of atypical neoplastic, often pleomorphic cells that invade other tissues. "In these cases, MN has been described by specifying the associated antigen and condition, such as THSD7A-associated MN with malignancies." (PMID 41445719, 2025). "In the study of tumor pathogenesis, uncontrolled angiogenesis is considered a hallmark of malignant tumors, and studies have confirmed that THSD7A participates in the invasion, metastasis and generation of tumor vessels." (PMID 38686366, 2024). "In studies concerning THSD7A-positive malignancy-associated MN, the associated cancers are highly diverse, including breast, lung, and digestive system cancers." (PMID 38686366, 2024). "Further, antibodies against glomerular antigen THSD7A can be associated with an increased risk of cancer-associated MGN." (PMID 36893151, 2023). "Antigen-specific IgG subclasses and their association with cancer were studied in patients with anti-PLA2R antibodies or anti-THSD7A antibodies." (PMID 33828546, 2021). "In a large Chinese study, anti-THSD7A antibodies were positive in only 2% of patients with cancer-associated MN." (PMID 33828546, 2021). "In a few case reports, THSD7A-related MN seems to be clearly linked to cancer because the antigen was found in tumor cells and the patients achieved remission after efficacious anticancer therapy." (PMID 33562791, 2021). "Although the association between THSD7A and cancer is disputed, THSD7A can be detected in the tumor, metastatic lymph node cells, and dendritic cells of lymph nodes." (PMID 33042109, 2020). "Nonetheless, given the relatively high rate of comorbidity (2 of 14 case), intensive cancer surveillance is warranted for THSD7A-associated MN." (PMID 30868298, 2019). "In THSD7A-ab positive patients antigen-specific IgG1, IgG2, and IgG3 were found in 65, 21, and 62% of cases with primary MN vs. 71, 29, and 86% of cases with malignancy-associated MN, respectively." (PMID 30619370, 2018). "We reviewed all patients referred to us over a 14-year period to revisit in a single centre the diagnostic, prognostic and predictive value of PLA2R-Ab, as well as the prevalence and potential cancer association of anti-THSD7A antibodies." (PMID 28257452, 2017). "Apart from exceptional cases where THSD7A-Ag was found in the tumor and dendritic cells in a metastatic lymph node, the causality link between MN and the cancer is often difficult to establish." (PMID 28257452, 2017). "This is of special importance because THSD7A, as a membrane-associated protein, might serve as a putative therapeutic target in cancer therapy." (PMID 36673031, 2023). "At least, strongly SCARA5-positive cancers were associated with THSD7A-positivity." (PMID 37443605, 2023). "Furthermore, we were also unable to include the biopsies of patients with cancers and secondary MN to assess if THSD7A shows any association in such patients in our population." (PMID 33413188, 2021). "We observed mutations also in THSD7A gene, coding for a new potential tumor antigen that might represent a putative therapeutic target for cancer therapy." (PMID 33915956, 2021). "Furthermore, approximately 20% of patients with THSD7A-associated MN are diagnosed with malignancy within a median time of 3 months since the diagnosis of MN, indicating that THSD7A-associated MN is related to an increased risk of malignancy." (PMID 34337081, 2021). "Recent studies have also shown a possible relationship between THSD7A-associated MN and cancer." (PMID 31705303, 2020). "Based on the reports of THSD7A-associated MN with malignancy and the pathogenesis of MN, lymph node metastasis may be a risk for cancer-related MN." (PMID 30727973, 2019). "THSD7A-associated MN is significantly associated with malignancies." (PMID 31447839, 2019).
cancer (continued). "We propose a revised clinical workup flow for patients with MN that recommends assessment of kidney biopsy for PLA2R1 and THSD7A antigen expression, screening for circulating anti-podocytes antibodies, and assessment for secondary causes, especially cancer, in patients with THSD7A antibodies." (PMID 29511687, 2018). "There is some indication that patients with anti-THSD7A antibody may have a higher risk of cancer." (PMID 28257452, 2017). "Although Thsd7a could promote cancer, it may be associated with high differentiation." (PMID 28947992, 2017). "We discovered a single SEV cargo that was altered in endoglin-KD cancer SEVs, the transmembrane protein Thrombospondin Type 1 Domain Containing 7A (THSD7A)." (PMID 41532547, 2026). "Further investigation revealed that THSD7A is present on both cancer cell and neuronal exosomes and that recombinant purified THSD7A is sufficient to rescue filopodia defects resulting from exosome inhibition in both cell types." (PMID 41532547, 2026). "To validate our finding that THSD7A levels are downregulated in SEVs from endoglin-KD cancer cells, we performed Western blot analysis of control and endoglin-KD SEVs from B16F1 and HT1080 cells." (PMID 41532547, 2026). "We further found that both cancer cell and neuronal SEVs carry THSD7A and that add-back of purified THSD7A is sufficient to rescue filopodia defects of both endoglin-KD cancer cells and exosome-inhibited neurons." (PMID 41532547, 2026). "Recent advancements in the identification of MN-specific antigens, such as THSD7A and NELL-1, suggest a potential association with malignant tumors, yet definitive proof of this relationship remains elusive." (PMID 38686366, 2024). "In vitro cell culture experiments knocking out THSD7A can inhibit cancer cell proliferation and migration also confirm this mechanism." (PMID 38686366, 2024). "In German and American cohorts, multiple studies indicated that the proportion of patients with THSD7A-positive MN combined with malignant tumors ranged from 9% to 30%." (PMID 38686366, 2024). "Research has explored the expression of THSD7A in more than 70 types of malignant tumor tissues and found that THSD7A expresses differently in various tumors." (PMID 38686366, 2024). "To date, more than a dozen MN-related antigens have been identified, of which THSD7A and NELL-1 are thought to be associated with malignancies." (PMID 38686366, 2024). "Our goal is to highlight the importance of cancer screening in individuals with THSD7A-positive PMN." (PMID 36968937, 2023). "Evidence indicates that THSD7A is a potential tumor antigen in humans, participating in cancer progression, vascular invasion, angiogenesis, and metastasis in the tumor environment." (PMID 37658161, 2023). "In a former study, we analyzed the role of thrombospondin type-1 domain containing 7A (THSD7A) as a potential tumor antigen in cancer." (PMID 36673031, 2023). "A possible explanation is that the immune system forms an anti-THSD7A antibody that also attracts antibodies against THSD7A antigens in cancer cells." (PMID 37658161, 2023). "Gene set enrichment and immune infiltration analyses were used to determine the cancer-promoting mechanisms of THSD7A and its effect on the immune microenvironment." (PMID 37905960, 2023). "THSD7A expression is closely related to the metastasis, differentiation, and invasion of related malignant tumors." (PMID 36506585, 2022). "THSD7A is expressed by some cancers and it has been suggested that anti-THSD7A antibodies are associated with an increased risk of cancer-associated MN, and screening for cancer was recommended in patients with anti-THSD7A positive MN." (PMID 33828546, 2021). "Assessment of the cancerous tissues showed increased THSD7A mRNA levels and elevated THSD7A protein expression, suggesting that THSD7A was actively synthesized by cancer cells." (PMID 34337081, 2021).
cancer (continued). "Twenty percentage of the patients with THSD7A-associated MN in their cohort also had a malignant disease, while only 7% with PLA2R1-associated MN presented with cancer." (PMID 31705303, 2020). "In order to explore the relationship among THSD7A, tumor and MN, this study firstly explored the relationship between THSD7A and proteinuria in two types of cancers." (PMID 31443644, 2019). "But it’s difficult to explain phenomenon that there was a high prevalence of THSD7A expression in cancers, and there was a high prevalence of cancer in MN patients with THSD7A positive." (PMID 31443644, 2019). "Twelve genes were located in eight of the top-15 breakpoint regions, and six of these genes are associated with cancer (CACNA1B, IBSP, MEPE, NBEA, RELN and THSD7A)." (PMID 31249626, 2019). "Recently a study indicated that the expressing quantity of THSD7A was related to the clinical stages and differentiation degrees of numerous cancers." (PMID 31443644, 2019). "Their further analyzed the relationship between malignancies and MN, the results showed that 7(28%) of all 25 THSD7A positive MN patients had a malignant tumor." (PMID 31443644, 2019). "Among these 8 women out of 40 with THSD7A-related MN developed cancer within 3 months from the diagnosis of MN." (PMID 29511687, 2018). "In an intriguing paper from Japan, 8 patients with THSD7A related MN developed a malignancy within 3 months of follow-up." (PMID 29511687, 2018). "In order to better understand the role of THSD7A in MN (with or without malignancies), we performed a systematic review and meta-analysis to explore the prevalence of THSD7A in MN and the prevalence of malignancies in THSD7A-positive patients." (PMID 29623759, 2018). "That is to say, Thsd7a expression is higher for the cancer tissues of worse stage and better differentiation." (PMID 28947992, 2017). "Indeed, purified THSD7A was able to rescue filopodia defects in both endoglin-KD cancer cells and exosome-inhibited neurons." (PMID 41532547, 2026). "Altogether, we identify THSD7A carried by exosomes as a key controller of filopodia formation in diverse cell types and further identify endoglin as a key regulator of THSD7A secretion in exosomes in cancer cells." (PMID 41532547, 2026). "As endoglin seemed unlikely to directly induce filopodia formation and is not present in neurons, we performed quantitative proteomics of control and endoglin-KD SEVs and identified the transmembrane ECM protein THSD7A as regulated in cancer cell SEVs by endoglin." (PMID 41532547, 2026). "For example, PLA2R-, THSD7A-, or NELL1-associated MN has been detected in malignancies." (PMID 41445719, 2025). "In recent years, THSD7A has been studied not only in MN but also in malignant tumors." (PMID 38686366, 2024). "Enrichment analysis suggested that epithelial-mesenchymal transition and inflammatory responses may be potential pro-cancer mechanisms of THSD7A." (PMID 37905960, 2023). "This is of special importance because THSD7A might also serve as a putative therapeutic target in cancer therapy." (PMID 36673031, 2023). "Moreover, some studies have indicated that THSD7A inhibits endothelial cell migration and angiogenesis by binding to αVβ3 integrin, a potential factor for targeted therapy for cancer and related vascular diseases." (PMID 36506585, 2022). "Furthur studies have found that THSD7A may impact the biological processes of cancer cells via multiple tumor-related pathways, such as mTOR, Wnt, and MAPK." (PMID 36506585, 2022). "The finding that the expression of THSD7A differed according to the clinical stage and differentiation degree of various cancers suggests that THSD7A is involved in vascular invasion, cancer progression, metastasis, and angiogenesis mechanisms that support tumor growth." (PMID 34337081, 2021). "Data on THSD7A antibodies might be helpful to evaluate cancer development in MN patients in future studies." (PMID 32522167, 2020).
cancer (continued). "The reason for this lack of association between cancer and THSD7A-associated MN in our study cohort remains elusive and requires further investigation." (PMID 30868298, 2019). "It demonstrated that cancer patients with THSD7A positive were prone to have urinary protein, and THSD7A might be a link between cancers and proteinuria." (PMID 31443644, 2019). "THSD7A was found to be expressed in a variety of malignant tumors." (PMID 31443644, 2019). "A total of 9 patients with positive THSD7A had malignancies reported." (PMID 29623759, 2018). "After inclusion of the retrospective cohorts and analysis of samples derived from 1276 MN patients, 8 out of 40 patients with detectable anti-THSD7A antibodies presented with malignancy and the median time from diagnosis of MN and development or detection of malignancy was 3 months." (PMID 28904948, 2017). "However, the expressing state of Thsd7a in cancerous people as well as the effect on developing activity of cancer was still unrevealed." (PMID 28947992, 2017). "Given our new findings that endoglin is a key regulator of filopodia via regulating THSD7A trafficking to SEVs, an important future direction could be to test the contribution of THSD7A to endoglin-dependent phenotypes, including angiogenesis and cancer metastasis." (PMID 41532547, 2026). "Based on the observed decreases in THSD7A expression in SEVs from endoglin-KD cancer cells and the role of endoglin as a co-receptor that traffics through endosomes, we hypothesized that endoglin may alter the trafficking of THSD7A to SEVs/exosomes." (PMID 41532547, 2026). "Thrombospondin type-1 domain-containing 7 A (THSD7A) is a MN autoantigen and a secondary autoantigen of MN20, which has been found to be associated with the development of malignant tumors, with one study showing that THSD7A positivity in malignant tumors is 15–20%21." (PMID 37658161, 2023). "However, patients with positive THSD7A expression were prone to have malignancies." (PMID 31443644, 2019). "However, whether the patients with THSD7A-positive malignant tumors were more prone to kidney disease, and THSD7A is a bridge between malignant tumors and MN was still unclear." (PMID 31443644, 2019). "It implied that patients with THSD7A-positive MN might be prone to have malignant tumors." (PMID 31443644, 2019). "It suggested that THSD7A might be involved in development of various kinds of cancers." (PMID 31443644, 2019). "Thus, THSD7A represents a prime candidate for downstream validation of cancer involvement." (PMID 29531238, 2018). "Furthermore, endoglin and/or THSD7A could serve as potential targets for anti-cancer therapies." (PMID 41532547, 2026). "In this study, in order to clarify THSD7A's cancer-promoting function, mechanism, and suspected downstream genes in ESCC, we performed preliminary screening and validation of THSD7A's downstream driving genes." (PMID 35755171, 2022). "When the prevalence of cancer was analyzed per subcategory of MN identified by antigen, NELL-1 came first (33%) followed by THSD7A (11%) while PLA2R-positive cases accounted for only 4%." (PMID 33562791, 2021). "None of the samples of the secondary MN patients showed enhanced granular expression of THSD7A, whereas 1 of the 5 samples from the patients with HBV and 1 of the 8 samples from the patients with malignancies showed enhanced granular expression of PLA2R." (PMID 26393352, 2015). "Chromosomal region 7p22 is located in a fragile sequence (FRA7B) containing two miRNA genes (mir589 and mir339) and three large genes (SDK1, THSD7A, MAD1L1), and is highly prone to gaps and breaks in several cancers." (PMID 23626673, 2013). "Patients with MN who are negative for anti-PLA2R antibodies and positive for anti-THSD7A antibodies in serum should be further evaluated for cancer." (PMID 38965515, 2024).
cancer (continued). "The association between MN and cancer has been controversial, unlike PLA2R, which has been suggested to be a tumor suppressor, and patients with THSD7A-associated MN have a significantly increased risk of malignancy." (PMID 34337081, 2021). "A patient who had repeated renal biopsy showed negative expression of THSD7A in their kidney tissue in the first biopsy, however the second renal biopsy showed the MN lesion with positive THSD7A and manifested malignant tumor after 17 months." (PMID 33042109, 2020). "Testing for THSD7A antigen is only needed in cases of suspected primary MN that is negative for PLA2R1 antigen or cases suspected of having cancer-related MN." (PMID 29511687, 2018). "Therefore, there is currently no research to confirm the clear relationship between THSD7A-MN and malignant tumors." (PMID 38686366, 2024). "Whether our findings may or may not be transferred to patients with PLA2R1-ab and THSD7A-ab negative MN, especially in those patients with malignancies, who show a negative IgG4 staining in the biopsy remains an open question." (PMID 30619370, 2018).